MYC (MYC proto-oncogene, bHLH transcription factor)
Diseases named in the same sentence as MYC in open-access papers (continued):
Sharing a sentence is not in itself a finding about the gene and the disease.
tumor (continued). "Here we show that JQ1 does not inhibit MYC expression to a similar extent in all tumor cells." (PMID 24466310, 2014). "We showed previously that tumour onset could be accelerated by retroviral infection and a RIM screen identified a number of candidate third hit genes, including Pim1, a gene that accelerates tumour onset when combined with MYC/Runx2 in the germ-line." (PMID 24586197, 2014). "Also in these tumor cells, PI3K inhibition dose dependently reduced β-Catenin transcriptional activity and readily reduced the expression of the WNT target genes c-MYC, Cyclin-D1 and notably LEF-1." (PMID 24930890, 2014). "Our further results showed that GE treatment induced a differential expressional pattern of several tumor-related genes, including increased expression of two crucial tumor suppressor genes, p21 and p16, and decreased expression of two tumor promoting genes, BMI1 and c-MYC." (PMID 23342141, 2013). "This indicates that MYC alone is not capable of transforming lymphoid cells into neoplasia." (PMID 23369149, 2013). "Like most proteins, c-MYC is never found in isolation within normal or tumor cells." (PMID 23634284, 2013). "Not surprisingly, deregulation of MYC functions contributes to the tumor phenotype." (PMID 23717612, 2013). "While the results in tumor models suggest BRG1 is necessary for maintenance of proper gene expression and response to environmental stimuli, the abrogation of BRG1 most likely blocks nucleosomal responses initiated not only by MYC, but by other chromatin remodeling complexes as well." (PMID 23373009, 2013). "Besides MYC and RAS, let-7b can function as a tumor suppressor by blocking CYP2J2." (PMID 22761738, 2012). "This might suggest that FLIPL plays a role in the selection of MYC-induced lymphoid but not of myeloid tumor cells in this system." (PMID 22393362, 2012). "In contrast, c-MYC over-expression could be seen in a subset of tumours of the p1/h1, p2/h2, and p4/h4 subgroups, but not in any of the tumours assigned to the MNA-specific group p3/h3." (PMID 21492432, 2011). "Thus, in this context, pre-deletion of Rb does not affect tumor development in the liver of mice expressing MYC." (PMID 21573126, 2011). "This indicates that in some cell types MYC needs to cooperate with other survival genes, which may or may not be classical activated oncogenes or inactivated tumor suppressors, to transform cells." (PMID 20195545, 2010). "Low levels of MYC expression, which occurs physiologically during cell proliferation in most cell types, is generally tolerated by cells without engaging tumor suppressor mechanisms, whereas high levels of MYC expression generally induce apoptotic and other tumor surveillance pathways." (PMID 20195545, 2010). "Interestingly, we observed that MYC, an oncogene characterised by copy number gain in a wide variety of tumour types, was not significantly differentially expressed between amplified and unamplified groups of samples." (PMID 20386695, 2010). "In contrast, MYC transcription factors, including MYCN, also sensitize cells for apoptosis, a function that should inhibit tumor formation and that could also be involved in spontaneous tumor regression." (PMID 18851746, 2008). "It is possible therefore that an increase in MAD expression could be attributed to a negative feedback pathway to counteract aberrant MYC signalling and may be consistent with a role as a tumour suppressor." (PMID 18493233, 2008). "Interestingly, in contrast to most MYC-induced tumor models, MYC-induced lung tumors were not oncogene-addicted; whereas K-rasG12D inactivation did induce complete tumor regression in K-rasG12D–induced lung tumors." (PMID 18461184, 2008). "Second, tumor cells that had arisen from the transplantation of MMTV-rtTA/TRE-MYC/BCRHEL cells could not be further passaged in the absence of overexpressed MYC." (PMID 18578569, 2008).
tumor (continued). "A trivial explanation for doxycycline-independent tumor viability could be either the aberrant expression of MYC independent of doxycycline or endogenous upregulation of murine c-Myc." (PMID 18461184, 2008). "In addition, therapeutic approaches aimed at disrupting key regulatory interactions, including those involving TAF1, MYC, MAZ, and other TFs such as KLF15 and ZNF281, may suppress tumor growth and modulate stress adaptation, thereby enabling more precise interventions against cancer." (PMID 41155227, 2025). "Moreover, as a cytotoxic agent and an inhibitor of mitochondrial respiratory Complex I that disrupts the ATP production in tumor cells, it remains to be determined whether squamocin can trigger a lethal UPR in human carcinoma, particularly in cancers with MYC activation." (PMID 39823459, 2025). "Interestingly, IF analyses, as well as ChIP assays, fully recapitulated what was previously observed in BJ‐EHLT cells, indicating that the ability of KHSRP to bind the G4 structures located within the promoter regions of c‐KIT and c‐MYC is a generalizable phenomenon, independent of tumor histotype." (PMID 39763191, 2025). "ANXA7 upregulation may thus chemo-sensitize the tumor if p21 modulators are added to the treatment regimen, as they will counteract the c-MYC overexpression and oncogenic drive towards stemness, which has the same effect as c-MYC inhibition in these conditions." (PMID 39684934, 2024). "A non-randomized, open-label phase II trial of arginine deiminase in ASS1-low SCLC patients was terminated due to slow patient accrual and lack of tumor response after 22 patients had been enrolled, though patient stratification based on factors such as MYC expression may be beneficial." (PMID 39456533, 2024). "Thus, the genomic analyses strongly suggest that, while FOXO1AAA might not affect c-MYC cancer development per se, but it could modify the gene expression patterns, especially metabolic pathway genes, of the tumor." (PMID 39325536, 2024). "Hence, we consider it of interest to further evaluate prospectively whether the knowledge of candidate biomarker status, such as MYC amplification, outweighs the potential negative effects risked by taking a preoperative tumour biopsy." (PMID 38536546, 2024). "In addition, isolated cases of MYC methylation class AT/RT and WNT-activated medulloblastoma have been shown to present EZHIP positivity, but this was only focal (<1% of positive tumor cells), and thus, this was not to considered as true EZHIP overexpression (>90% of positive tumor cells)." (PMID 38544524, 2024). "Interestingly, the intraperitoneal injection of immortalised MSCs transformed with a proto-oncogene MYC did not appear to have a pro-tumorigenic role in initiation or anchorage-independent growth at pre- or post-exosome production of HNC tumours in an animal model." (PMID 39120301, 2024). "Observations reported here suggest that Clinical Laboratory Improvement Amendments (CLIA)–certified c-MYC analysis and scoring of tumor biopsies may be necessary to accurately determine relative c-MYC expression levels, rather than analysis of genomic DNA or RNA alone." (PMID 36719686, 2023). "In addition, oncogenic MYC signaling could overexpress CD47 and PD-L1 on tumor cells." (PMID 37546397, 2023).
tumor (continued). "However, MYC expression contributes to the development and progression of aggressive HCC as there was a greater distribution of patients with higher grade tumors (neoplasm histologic grade 3 or 4) in the MYCHi group versus the MYCLo group (42.62% vs. 31.18%) (Figure 4cii,iii)." (PMID 36684069, 2023). "In other words, tumor biology in mCRPC may not be as aggressive in a patient with only an AR amplification compared to those whose malignancy has multiple GAs that include AR (such as MYC, BRAF, PIK3CA, and others)." (PMID 38450313, 2023). "HIF1A-As2 guides its binding protein DHX9 to stimulate MYC signalling, whereas activated MYC, in turn, could transcriptionally activate HIF1A-As2 expression, suggesting HIF1A-As2 and MYC form a double-positive loop that may robustly alter downstream genes and tumor growth." (PMID 37041291, 2023). "However, despite a detectable MYC promoter signal, almost no accessible chromatin could be detected at RhOME1-3 in normal cells, suggesting that these super-enhancers are tumor-specific in at least these samples." (PMID 38040699, 2023). "Furthermore, TAMs promote tumor progression and invasion by secreting matrix metalloproteinases (MMPs), and of these, MMP1 can activate cdc25a/CDK4-cyclin D1 and p21/cdc2-cyclin B1 complexes to accelerate the growth of colon cancer cells via the regulation of MYC expression." (PMID 36966168, 2023). "We also recognize tumor samples presenting with a simple karyotype (i.e., a MYC R with one or two additional aberrations) may not be suitable for AI; however, we should highlight that DLBCL and large B‐cell lymphomas with MYC R often present with complex karyotypes." (PMID 36051032, 2022). "As (i) MYC tumors express lower levels of active DNA demethylases as well as other genes being involved in DNA demethylation, and (ii) DNMTs are upregulated in RT56,57, we hypothesize that their inhibition impacts tumor outcome through counterbalancing the epigenetic status of these tumors." (PMID 35318328, 2022). "Given that the spleen is a hospitable site for Vk*MYC cells to reside, it is possible that the increased splenic tumour burden in HFD mice may not be due to changes in metabolic signalling but rather an increased availability of MM niches resulting from HFD-induced splenomegaly." (PMID 35908046, 2022). "Moreover, CDK16 inhibition downregulated MYC and PD‐L1 in NSCLC cells, suggesting that the enhanced antitumor immune response may be a downstream effect of inducing cancer cell senescence to exercise its tumor‐suppressive function." (PMID 34687270, 2022). "Tumor-specific isoforms of BIN1, including exon 12A, are not able to interact with MYC because an intramolecular interaction occurs between the consensus class I SH3-binding domain, encoded by exon 12, and the SH3 domain, preventing MYC from binding to the SH3 domain of BIN1." (PMID 33801599, 2021). "However, MYCN non-amplified tumours often present high levels of expression of MYC (c-MYC), which might explain why PKM2 and hexokinase II levels were similar in vesicles from the two groups of patients." (PMID 34847775, 2021). "Additionally, miR-210 plays a regulatory role in the inhibition of cell cycle arrest during hypoxic conditions, particularly by suppressing the MYC proto-oncogene antagonist, and by facilitating cell growth of tumor cells even when oxygen is not immediately available." (PMID 34638272, 2021).
tumor (continued). "Additionally, high expression levels of c-MYC were demonstrated to regulate antitumor immune responses, by mediating programmed death ligand 1 (PD-L1) and cluster of differentiation 47 (CD47), as well as promoting CRC tumor recurrence after 5-fluorouracil (5-FU)-based adjuvant chemotherapy." (PMID 34440739, 2021). "Interestingly, MYC-driven proline biosynthesis requires NAD(P)H as cofactor and promotes NAD(P) accumulation: as a function of this recycling, proline biosynthesis interlocks with pathways that generate NAD(P)H, namely glycolysis and pentose phosphate pathway, and ultimately fosters tumor growth." (PMID 32932943, 2020). "Since MYC depends on PVT1 in its ability to drive malignant transformation and is itself difficult to target because it lacks enzymatic activity, several groups have speculated about the validity and feasibility to target PVT1 to weaken or inhibit MYC in tumor cells." (PMID 33134177, 2020). "While it cannot be excluded that MYC overexpression reshapes evolution of BRCA1-deficient TNBCs via negative selection of tumor cell clones with high levels of CNAs, amplifications of MCL1 might be particularly selected for as they may counteract the pro-apoptotic effects of MYC overexpression." (PMID 30674894, 2019). "Because tumor super-enhancers can encompass genomic regions as large as 200 kb, and CTCF occupies sites that occur on average every 10 kb, there is considerable opportunity for super-enhancers to adventitiously contain a CTCF-bound site, which in turn could serve to interact with the MYC CTCF site." (PMID 29641996, 2018). "Hence, IL-12-LNP does not suppress tumor growth by decreasing MYC expression." (PMID 30458889, 2018). "Both FOXO3A and MYC interact functionally with the forkhead binding element in the CDKN1B proximal promoter, meaning that MYC may inhibit the activation of CDKN1B by FOXO3A in tumor cells, potentially leading to the uncontrolled proliferation and invasiveness of a variety of tumors." (PMID 29124072, 2017). "Therefore, several recent studies have focused on indirect inhibition of oncogenic MYC activity using a synthetic lethal approach in targeting drugable proteins that are essential for the viability of MYC activated tumor cells but not for cells without MYC activation (a synthetic lethal approach)." (PMID 28192473, 2017). "Hence, although not yet proven, CAV1 could play a role in c-MYC-driven glutamine metabolism in tumours." (PMID 27852311, 2016). "Therefore as a MYC transcriptional target, TFAP4 may play a critical role in cancer cells in concert with deregulated MYC, by coordinating the expression of specific genes that are essential for tumor progression." (PMID 27448979, 2016). "Additionally, Ingenuity Pathway Analysis (IPA) did not predict c-MYC activation in KPH2 tumours." (PMID 26837714, 2016). "These four mechanisms—MYC genomic gain (9% of O1 tumours), MAX genomic loss (35% of O1 tumours), MYC exon 3 hypomethylation (20% of O1 tumours) and mir34b/c locus hypermethylation (28% of O1 tumours)—were not all required to observe an increase of MYC activity." (PMID 27090007, 2016). "Interestingly, two tumor-suppressive miRNAs, let-7 and miR-34, are the most common altered miRNAs in NSCLC tumor tissue The reduction in let-7 and miR-34 expression is relevant in the NSCLC oncogenic phenotype and is involved in the maintenance of oncogene addiction, via RAS, BCL2, MET or MYC." (PMID 26425674, 2015).
tumor (continued). "The depletion of MYC translocations in HiGA-SIR and its favorable patient outcome in our extended DLBCL cohort indicated that the lower tumor cell content in HiGA-SIR was likely due to the underlying biology of the tumor cells and not to the way in which the tumor samples were collected." (PMID 24223701, 2013). "Studies done using a MYC conditional osteosarcoma transgenic mouse model supported this proposed model and gave evidence that oncogene-driven-malignant transformation can be suppressed if the cancer cells are in a tumor non-permissive location within the niche." (PMID 24709643, 2013). "The present investigation was undertaken to determine whether the protooncogene c-MYC may come under negative regulation by p150, consistent with the frequent overexpression of c-MYC in many forms of cancer and with the action of p150 as a putative tumor suppressor." (PMID 23029531, 2012). "With the Wilcoxon rank test we find genes such as MYC, CCNE1, KRAS, NDRG1, MLL4 and MTSS1 for which data set specific normal tissue expression may not be significantly different from all tumor samples but is variable between low and high copy number tumor samples." (PMID 22174824, 2011). "Thus, whether or not MYC and K-rasG12D functionally cooperate to activate critical tumor promoting pathways appears to depend upon the specific tissue context." (PMID 18461184, 2008). "Despite the strong evidence that MYC is important, the requirements may differ when the selection conditions are changed, and we have preliminary evidence that MYC may not be required in ERα/BMI/TERT-transduced HMECs, at least for the initial stages of tumour formation." (PMID 17573968, 2007). "We hypothesise that MYC overexpression may be favourable for the proliferation of benign hyperplastic cells, but may not be required for the maintenance and progression of the tumour." (PMID 17146477, 2007). "Furthermore, the identification of oncogenes such as KRAS, MYC, and PIK3CA as being more effective targets than tumor suppressor genes (effect size: 0.87 vs 0.79, P = .03) suggested that oncogene knockout could be a more potent strategy for tumor growth control." (PMID 41517680, 2026). "In addition to its role in restoring MHC-I expression, EZH2 inhibitors may have further tumor-suppressive effects on SCLC through broader transcriptional reprogramming, which includes the hyperactivation of ribosome biogenesis, epithelial-mesenchymal transition, and MYC targets." (PMID 41353272, 2025). "The three adult cases lacked MYC translocation; two showed diffuse positivity for both TdT and CD34, and the remaining case was TdT‐positive in ~80% of tumour cells but lacked any CD34 expression." (PMID 41047873, 2025). "MYC-driven circRNAs were found to be upregulated in tumors such as triple-negative breast cancer (TNBC) and SCLC and can promote tumor progression in these cells." (PMID 40126351, 2025). "Specifically, MYC showed positive correlations with oncogenic factors HDAC2, HDAC3, AKT2, and AKT3, while demonstrating negative correlations with tumor suppressors PTEN and FOXO1." (PMID 40229260, 2025). "Using the ID8 murine OC cell line transduced with c-MYC or KRAS, researchers found that both oncogenes markedly accelerated tumor progression in vivo, despite no increased proliferation in vitro." (PMID 41020848, 2025). "Additionally, given that MUC1-C transcriptionally cooperates with NF-κB and MYC to drive PD-L1 expression, silibinin’s known suppression of NF-κB and MYC signaling may further destabilize MUC1-C-driven transcriptional programs, weakening its immunosuppressive influence in the tumor microenvironment." (PMID 40650040, 2025). "Immunohistochemically, the tumor exhibited diffuse positivity for CD31 and ERG, with no discernible expression of MYC and negativity for TRPS1." (PMID 38902365, 2025).